HDGF (heparin binding growth factor)
Diseases named in the same sentence as HDGF in open-access papers (continued):
Sharing a sentence is not in itself a finding about the gene and the disease.
atherosclerosis (2 papers, 2023 to 2025). A disease characterized by the build-up of fatty material and calcium deposition in the arterial wall resulting in partial or complete occlusion of the arterial lumen. "HDGF knockdown alleviated inflammation, glycolysis, and lipid accumulation in M1 macrophages, while high METTL3 expression in macrophages increased HDGF levels through m6A modification, thereby aggravating atherosclerosis." (PMID 37671161, 2023). "explored the pathogenesis of atherosclerosis from the perspective of macrophage polarization and energy metabolism and found that HDGF was highly expressed in the aortas of patients with atherosclerosis and APOE knockout mice, as well as in M1 macrophages." (PMID 37671161, 2023). "During atherosclerosis, METTL3 regulates hepatoma-derived growth factor (HDGF) mRNA stability in macrophages through m6A modification, increasing HDGF expression that, in turn, accelerates glycolysis and enhances mitochondrial dysfunction." (PMID 40066451, 2025).
fibrosis (2 papers, 2013 to 2023). the formation of excess fibrous connective tissue in an organ or tissue in a reparative or reactive process. "HDGF also accelerates the formation of hepatic fibrosis by collaborating with TGF-β in murine models." (PMID 37827291, 2023).
head and neck carcinoma (2 papers, 2019 to 2025). A carcinoma that arises from the head and neck region. "In vitro assays revealed that HDGF depletion significantly attenuated proliferation, migration, and invasion, aligning with reports linking HDGF to poor prognosis in head and neck carcinomas and extending its mechanistic role specifically to HSCC." (PMID 41278276, 2025).
head and neck squamous cell carcinoma (2 papers, 2005 to 2022). A squamous cell carcinoma that arises from any of the following anatomic sites: lip and oral cavity, nasal cavity, paranasal sinuses, pharynx, larynx, and salivary glands. "Absence or low levels of Hsulf-1 in hepatocellular, ovarian, and head and neck squamous cell carcinoma cell lines were associated with up-regulation of heparin-binding growth factor signaling." (PMID 15817123, 2005). "Hsulf-1 is a newly identified enzyme, which has the ability to decrease the growth of hepatocellular, ovarian, and head and neck squamous cell carcinoma cells by interfering with heparin-binding growth factor signaling." (PMID 15817123, 2005).
myocardial infarction (2 papers, 2013 to 2022). Gross necrosis of the myocardium, as a result of interruption of the blood supply to the area, as in coronary thrombosis. "GAPDH, GNAS, and ACTB were shown to be the most stable genes in platelets of healthy individuals, while HDGF, GNAS, and ACTB were the most stable in platelets of patients with the history of myocardial infarction." (PMID 23389042, 2013). "We found GAPDH, GNAS, and ACTB to be the best combination of reference genes for platelet transcript level studies in healthy individuals, while HDGF, GNAS, and ACTB are the best for studies in patients with the history of myocardial infarction." (PMID 23389042, 2013). "Our results indicate that GAPDH, GNAS, and ACTB are the most stable genes expressed in platelets of healthy individuals and HDGF, GNAS, and ACTB were identified as the most stable reference genes expressed in platelets from patients with the history of myocardial infarction." (PMID 23389042, 2013).
pancreatic ductal carcinoma (2 papers, 2009 to 2020). "We studied the HDGF expression in a total of 50 patients with primary ductal pancreatic carcinoma, and reported that the HDGF expression, as evaluated by immunostaining, could be an independent prognostic factor for pancreatic ductal carcinoma after curative resection." (PMID 32545762, 2020).
viral infection (2 papers, 2014 to 2022). "In the case of AdV infection at a low MOI, which is similar to the condition for native viral infection, the growth of HDGF-expressing VA-deleted AdVs was much lower than that for GFP-expressing VA-deleted AdVs as well as FG AdVs." (PMID 25275311, 2014). "Since the replication of the viral genome occurs at around 8 h after infection, these results showed that the suppression of HDGF and TIA-1 began during the early and late phases of viral infection, respectively." (PMID 25275311, 2014). "Therefore, VA RNAs suppressed HDGF expression under the conditions other than viral infection, and a smaller amount of VA RNA than TIA-1 was sufficient to suppress HDGF." (PMID 25275311, 2014).
alcohol abuse (1 paper, 2025). The use of alcoholic beverages to excess, either on individual occasions ("binge drinking") or as a regular practice. "Database correlation analysis showed elevated HDGF expression in males and individuals with a history of alcohol abuse." (PMID 41278276, 2025). "Our bioinformatic analysis of TCGA data confirmed HDGF overexpression in HSCC tissues compared to normal tissues, and revealed associations with higher grade, advanced stage, male gender, alcohol abuse, lymphovascular invasion, and post-radiation status." (PMID 41278276, 2025).
autoimmune disease (1 paper, 2017). A disorder resulting from loss of function or tissue destruction of an organ or multiple organs, arising from humoral or cellular immune responses of the individual to their own tissue constituents. "Emerging evidence suggests that two heparin-binding growth factor, midkine and pleiotrophin are implicated in the pathogenesis of autoimmune diseases including SLE." (PMID 27903979, 2017).
cervical adenocarcinoma (1 paper, 2014). An adenocarcinoma arising from the cervical epithelium. "In the present study, the expression levels of HDGF in 63 patients with cervical adenocarcinoma undergoing surgery and the relationship between the HDGF expression and clinical pathological features and prognosis were analyzed." (PMID 25421244, 2014). "HDGF overexpression is common in early-stage cervical adenocarcinoma and is involved in the carcinogenesis of cervical adenocarcinoma." (PMID 25421244, 2014). "However, no reports have evaluated the correlation of HDGF expression with clinical pathological features and prognosis in cervical adenocarcinoma." (PMID 25421244, 2014).
COVID-19 (1 paper, 2023). A disease caused by infection with severe acute respiratory syndrome coronavirus 2. "Among these TFs-genes, HDGF, SUPT5H and MLLT1 with 4 edges was considered as key TF-genes which was highly related with regulation of T cell differentiation in elderly COVID-19 patients." (PMID 36966292, 2023). "The TFs-genes network showed that HDGF, SUPT5H and MLLT1, with the most edges, played important roles in age-related processes of COVID-19." (PMID 36966292, 2023).
Down syndrome (1 paper, 2025). "Therefore, while HDGF is useful for improving the diagnosis and prognosis of PH, as demonstrated here, its levels can be altered in genetically distinct populations such as individuals with Down syndrome." (PMID 41239459, 2025). "However, Yang and colleagues later found that Endostatin, Galectin-3, HDGF, and ST2 were also elevated in subjects with Down syndrome, regardless of PH status." (PMID 41239459, 2025).
epidermoid cysts (1 paper, 2011). "It is not clear why Ink4a+/- mice develop epidermoid cysts after a single neonatal UVB-treatment, but our results show that additional HDGF-deficiency leads to more and larger epidermoid cysts." (PMID 22014102, 2011). "Notably, epidermoid cyst associated melanocytes from wildtype animals showed a strong HDGF staining, whereas melanocytes in healthy, untreated wildtype hair follicles express HDGF just to a very low extend." (PMID 22014102, 2011). "Thus, HDGF-/-/Ink4a+/- mice developed significantly more and larger epidermoid cysts compared to both HDGFTyr/Ink4a+/- and Ink4a+/- mice." (PMID 22014102, 2011). "Interestingly, not HDGF overexpression but HDGF-deficiency led to the development of an increased number and size of epidermoid cysts after UVB-treatment." (PMID 22014102, 2011). "As expected, no HDGF-expression could be detected in epidermoid cysts derived from HDGF-/-/Ink4a+/- mice." (PMID 22014102, 2011).
gastric adenocarcinoma (1 paper, 2018). "The effect of H. pylori infection on HDGF expression was analyzed in human gastric adenocarcinoma cells." (PMID 30513684, 2018).
glomerulonephritis (1 paper, 2017). A renal disorder characterized by damage in the glomeruli. "Investigating toxic changes of biomarkers referred to primary glomerulonephritis revealed a substantial impact of APAP on the heparin-binding growth factor HBEGF at 8 h (Benjamini–Hochberg corrected p = 0.0026, 95% CI = [0.42, 0.96], two-sample t-test)." (PMID 28151932, 2017).
Hepatic steatosis (1 paper, 2026). Steatosis is a term used to denote lipid accumulation within hepatocytes. "Hepatic HDGF deficiency profoundly protects mice from high-fat, high-sucrose diet-induced hepatic steatosis and inflammation." (PMID 42063330, 2026). "Mechanistically, HDGF promotes lipogenesis and hepatic steatosis by facilitating S6K1-dependent phosphorylation of STAT3 at Ser727." (PMID 42063330, 2026).
Hepatitis (1 paper, 2023). Inflammation of the liver. "HDGF induces TNF-α/IL-1β/IL-6/COX-2 signaling in response to concanavalin A-induced hepatitis in vitro and in vivo." (PMID 37827291, 2023). "We also found that HDGF was involved in various liver diseases, such as liver fibrogenesis and concanavalin A-induced hepatitis." (PMID 37827291, 2023).
hilar cholangiocarcinoma (1 paper, 2020). A cholangiocarcinoma that arises from the junction, or adjacent to the junction, of the right and left hepatic ducts. "Based on their multivariate analysis, they concluded that the expression of HDGF was an independent prognostic factor for hilar cholangiocarcinoma." (PMID 32545762, 2020).
Huntington disease (1 paper, 2023). Huntington disease (HD) is a rare neurodegenerative disorder of the central nervous system characterized by unwanted choreatic movements, behavioral and psychiatric disturbances and dementia. "Moreover, lack of endogenous HDGF exacerbated motor impairments and reduced the life span of R6/2 Huntington’s disease mice." (PMID 37580082, 2023).
hypopharyngeal squamous cell carcinoma (1 paper, 2025). "Hypopharyngeal squamous cell carcinoma (HSCC), an aggressive HNSCC subtype characterized by high metastatic potential and poor prognosis, frequently overexpresses hepatoma-derived growth factor (HDGF), a factor implicated in tumor progression." (PMID 41278276, 2025).
ischemic disease (1 paper, 2022). Lack of blood supply to an area of the body, resulting in impairment of tissue oxygenation. "The heparin-binding growth factor midkine stimulates neo-angiogenesis in ischemic diseases, coordinates neutrophil influx, and raises blood pressure through stimulated angiotensin synthesis." (PMID 35211826, 2022).
leukemia (1 paper, 2020). A malignant (clonal) hematologic disorder, involving hematopoietic stem cells and characterized by the presence of primitive or atypical myeloid or lymphoid cells in the bone marrow and the blood. "Other hits in the experiment were soluble proteins as midkine, a heparin-binding growth factor that is overexpressed in many tumors and leukemia." (PMID 32575403, 2020).
lung squamous cell carcinoma (1 paper, 2023). "Studies have shown that targeting HDGF by miRNAs or antibodies is effective in inhibiting the growth of NSCLC or lung squamous cell carcinoma." (PMID 37301856, 2023).
myeloma (1 paper, 2025). "In this context, 2 key myeloma markers, MYC and DKK1, as well as many other cancer-associated genes, including ADM, HDGF, IL15, HGF, STMN1, CDKN1B and CD82, were potentially regulated by the predicted ligands." (PMID 41056512, 2025).
neuroblastoma (1 paper, 2019). Neuroblastoma (NB) is the most common solid, extracranial childhood tumor. "Clomipramine and lithium chloride are capable of potentiating vinorelbine cytotoxicity and Midkine, a heparin-binding growth factor, is not a resistance factor for the treatment of neuroblastoma cell lines with the mentioned drugs." (PMID 31191243, 2019).
neuropathy (1 paper, 2021). A disorder affecting the nervous system that manifests with pain, tingling, numbness, and/or muscle weakness. "The rat model of neuropathy used in this study showed that RTX injections decreased the mechanical threshold for pain, upregulated TNF-α inflammation in the DRG, and upregulated expressions of HDGF, PI3K, p-Akt/Akt, TrkB, iNOS, and substance P in the spinal cord." (PMID 33727914, 2021).
psoriasis (1 paper, 2025). An autoimmune condition characterized by red, well-delineated plaques with silvery scales that are usually on the extensor surfaces and scalp. "Midkine is a heparin-binding growth factor broadly expressed in inflammatory diseases; recent studies have shown that MK regulates VEGF-A expression via the Notch2/HES1/JAK2-STAT5A signaling pathway, thereby exerting critical effects on angiogenesis in psoriasis." (PMID 40959079, 2025).
R6 (1 paper, 2023). "To test whether HDGF expression is altered in HD, we first evaluated HDGF levels in various brain regions of R6/2 HD mice and control littermates by Western blot." (PMID 37580082, 2023).
retinal disease (1 paper, 2025). "Our findings establish HDGF as a novel therapeutic agent for AMD, uniquely capable of concurrently targeting the interconnected pathways of ferroptosis and mitochondrial dysfunction, thereby addressing a critical unmet need in retinal disease treatment." (PMID 41462634, 2025).
Sciatica (1 paper, 2021). Pain in the lower back and hip radiating in the distribution of the sciatic nerve. "The comparisons in this study revealed significantly higher levels of serum HDGF in the sciatica patients compared to normal controls." (PMID 33727914, 2021). "The serum level of HDGF was higher in sciatica patients compared to normal controls." (PMID 33727914, 2021).
squamous cell carcinoma (1 paper, 2019). A carcinoma arising from squamous epithelial cells. "Similarly, K19N mutation in HDGF (Lys19 in HDGF corresponds to Lys18 in HRP3) was found in squamous cell carcinoma." (PMID 31162607, 2019).
tumor (149 papers, 2008 to 2026). "Several regulatory mechanisms of HDGF are associated tumor progression, including PI3K/AKT and ERK signaling pathway activation, podosome formation, epithelial-mesenchymal transition promotion, and vascular endothelial growth factor (VEGF) induction." (PMID 37827291, 2023). "Circ-CDYL, the most significantly upregulated circRNA in a ncRNA network from a validated tumor tissue, interacts with the target genes encoding hepatoma-derived growth factor (HDGF) and hypoxia-inducible factor asparagine hydroxylase (HIF1AN)." (PMID 36300115, 2022). "According to the aggregate indicators of diagnostic efficiency, heparin-binding growth factor, glypican-3, and osteopontin are the most promising tumor markers of those studied." (PMID 34513063, 2021). "As the invasive ability of tumor cells is often correlated with the production of secretory proteases, the effect of HDGF knockdown on the expression of tumor invasion-associated secretory proteases MMPs including MMP2 and MMP9 were determined." (PMID 29300772, 2018). "Moreover, decreasing m6A has demonstrated potential therapeutic efficacy through the regulation of the YAP/CCNE1, HDGF, and cAMP pathways, which are commonly associated with tumor proliferation." (PMID 40136363, 2025). "However, it caused significant tumor shrinkage in the HDGF sgRNA2 group, suggesting that HDGF knockdown improved gefitinib sensitivity." (PMID 37301856, 2023). "We determined the association between HDGF and tumor growth in xenograft mice." (PMID 37301856, 2023). "HDGF encodes for a protein with DNA-binding mitogenic activity involved in cell proliferation and differentiation and is extensively described to be an angiogenic factor in several organs and tumours." (PMID 29614055, 2018). "Therefore, if HDGF exhibits oncogenic/transforming capacity on melanocytes, loss or overexpression of HDGF are expected to have an influence on tumor development and/or progression." (PMID 22014102, 2011). "Moreover, HDGF was found to be associated with tumor growth in a xenograft model in vivo." (PMID 32545762, 2020). "Spatial transcriptomics confirmed the colocalization of elevated lactylation activity and HDGF expression within tumor regions, linking metabolic reprogramming to the local microenvironment." (PMID 42245633, 2026). "Functional studies demonstrated that HDGF knockdown potently inhibited OS cell proliferation, migration, invasion, and tumor growth in vivo." (PMID 42245633, 2026). "In vivo experiments confirmed that, compared with using 5-FU or oxaliplatin alone, the combination of HDGF KO with 5-FU or oxaliplatin can further inhibit tumor growth in mice." (PMID 40001585, 2025). "The results reveal that the HDGF KO 5-FU treatment group had a significantly reduced tumor cell proliferation rate and increased tumor cell apoptosis rate compared with the WT 5-FU treatment group." (PMID 40001585, 2025). "As HDGF facilitates tumor angiogenesis and growth, YBX1’s stabilization of these mRNAs directly contributes to the metastatic phenotype." (PMID 41301491, 2025). "Analysis of TCGA data revealed that HDGF mRNA expression was significantly higher in HSCC tumor tissues compared to normal tissues in both unpaired and paired samples." (PMID 41278276, 2025). "Our results reveal that HDGF plays a critical role in facilitating HR-mediated DNA repair, thereby driving tumor progression and resistance to chemotherapy and PARP inhibitors in CRC." (PMID 40001585, 2025). "For instance, the role of METTL3 in stabilizing oncogenic transcripts such as HDGF and long non-coding RNAs (e.g., PSMA3-AS1, MIR22HG) is strongly linked to GCSC self-renewal and tumor initiation capacity." (PMID 41228380, 2025).